LIF (LIF interleukin 6 family cytokine)
Diseases named in the same sentence as LIF in open-access papers (continued):
Sharing a sentence is not in itself a finding about the gene and the disease.
muscle atrophy (1 paper, 2022). "LIF has been observed to be over-expressed in muscle atrophy disease, suggesting that LIF may be related to muscle atrophy." (PMID 35740622, 2022).
myelodysplastic syndrome (1 paper, 2016). A clonal hematopoietic disorder characterized by dysplasia and ineffective hematopoiesis in one or more of the hematopoietic cell lines. "TNF-α is known to induce LIF expression through p38MAPK signaling pathway in bone marrow stromal cells from pediatric patients with myelodysplastic syndrome and neuronal retinal cells." (PMID 26839969, 2016).
myeloma (1 paper, 2025). "In 2017, it was again reported to be a promising agent for inhibiting myeloma cell growth, interestingly reducing the phosphorylation of STAT3 but not ERK in response to IL-6 and LIF stimulation." (PMID 40895548, 2025).
nephrosclerosis (1 paper, 2017). Hardening of the kidney due to infiltration by fibrous connective tissue (fibrosis), usually caused by renovascular diseases or chronic hypertension. "Nonetheless, LIF administration in vivo in two different models of nephrosclerosis curtails myofibroblastic transformation in a way similar to in vitro data." (PMID 28297566, 2017).
neural tumors (1 paper, 2009). "While LIF protein has distinct functions in human and mouse ESC, its role in NSC generally is less well understood and there is not currently any evidence of a distinct role for LIF in NSC or neural tumors of different species." (PMID 19495417, 2009).
neuroendocrine tumors (1 paper, 2022). "LIF may be utilized for signaling mediated by GDNF and may be important in the pathobiology of neuroendocrine tumors." (PMID 35311096, 2022).
ocular hypertensive (1 paper, 2021). "Data illustrated an increase in the leukemia inhibitory factor (LIF) and IL-6 in ocular hypertensive animals." (PMID 33628191, 2021). "We have shown that both LIF and STAT3 mRNA expression and STAT3 phosphorylation at tyrosine 705 were increased in the ocular hypertensive animals, which were fully blocked by SNC-121 treatment, suggesting that LIF might be required for the STAT3 activation for pro-inflammatory cytokines production." (PMID 33628191, 2021).
oral cancer (1 paper, 2020). "In this study, we identified a relationship between LIF and major risk factors for oral cancer such as tobacco smoking, betel nut chewing, and alcohol consumption." (PMID 31973037, 2020). "The result supports the assumption that, in vitro, INHBA influences LIF-associated metastasis in oral cancer." (PMID 31973037, 2020). "Also, the relationship between LIF and the risk factors of oral cancer such as tobacco smoking, betel nut chewing, and alcohol consumption is unclear." (PMID 31973037, 2020). "Based on our findings, rLIF and the transfection of LIF expression vector confirmed that both exogenous and endogenous LIF induced oral cancer motility." (PMID 31973037, 2020). "To clarify the correlation between LIF expression and cancer metastasis in oral cancer, we used OSCC cell lines to investigate whether LIF plays a critical role in OSCC progression." (PMID 31973037, 2020). "Although LIF has been indicated as a novel biomarker and a prognostic target in various human cancers, its biological functions in oral cancer remain unknown." (PMID 31973037, 2020). "However, we found that LIF is essential for oral cancer transformation and malignant progression." (PMID 31973037, 2020). "To validate our findings, we determined the correlation between LIF and INHBA mRNA expression in patients with oral cancer by quantitative real-time PCR." (PMID 31973037, 2020). "On the basis of our findings, LIF was not involved in the mechanisms of tobacco smoking, betel nut chewing, and alcohol consumption related to oral cancer." (PMID 31973037, 2020). "In this study, we evaluated the correlation between LIF expression and the clinicopathological parameters of patients with OSCC and investigated whether LIF drives tumor progression in oral cancer." (PMID 31973037, 2020).
pancreatic (1 paper, 2022). "Next, we further confirmed the role of the circFARP1/LIF axis in GEM resistance in pancreatic xenograft tumor models." (PMID 35045883, 2022).
pelvic inflammatory disease (1 paper, 2024). Pelvic inflammatory disease (PID) is an acute or chronic inflammation in the pelvic cavity. "The mechanism by which modified Hongteng Baijiang decoction improves endometrial receptivity in sequelae of pelvic inflammatory disease rats may be related to the LIF/JAK2/STAT3 signaling pathway and gut microbiota." (PMID 38896093, 2024).
peritoneal disease (1 paper, 2022). "In addition to the presence of peritoneal disease, by the transcriptome analysis of paired samples of neoplastic tissue and normal gastric mucosa, we have identified a group of six differentially expressed genes that predict poor prognosis: ONG, FABP1, LIF, ONECUT2, SFRP2, and GPA33." (PMID 35847866, 2022).
polycystic ovary syndrome (1 paper, 2025). A disorder that manifests as multiple cysts on the ovaries. "It was determined that LIF mRNA expression decreased significantly on 4.5, 5.5, and 8.5 days of pregnancy in polycystic ovary syndrome rats." (PMID 40809179, 2025).
pulpitis (1 paper, 2025). Inflammation of the dental pulp. "These earlier results support our observation that LIF is associated with endodontic infections and that its expression is upregulated in dental pulp during pulpitis." (PMID 40701953, 2025).
renal fibrosis (1 paper, 2017). A final common manifestation of a wide variety of chronic kidney diseases characterized by glomerulosclerosis and tubulointerstitial fibrosis. "Most recently, LIF has been shown to attenuate renal fibrosis, but daily injections are required." (PMID 28297566, 2017). "In summary, these studies, through the evolution from EPC extract to LIF and then to hyper‐IL‐6, demonstrate the instructive role of microenvironmental cues and may provide in the future a facile strategy to prevent and reverse renal fibrosis." (PMID 28297566, 2017). "The component of EPC extract, LIF, is capable of preventing development of the contractile phenotype of activated fibroblasts but does not eliminate TGF‐β1‐induced collagen synthesis in cultured fibroblasts and renal fibrosis." (PMID 28297566, 2017).
retinal ischemia (1 paper, 2022). A ischemic disease that involves the retina. "Following retinal ischemia and retinal cell apoptosis induced by acute ocular hypertension, LIF and LIF receptor (LIF-R) expression were found to be increased, along with elevated levels of phosphorylated Akt." (PMID 35269741, 2022). "The study suggested that LIF may be critical for the process of degeneration/protection following retinal ischemia via activation of the Janus kinase (JAK)/STAT and Akt signaling pathways." (PMID 35269741, 2022).
salpingitis (1 paper, 2019). Acute or chronic inflammation of the fallopian tube. "The Ctr-driven amplification of LIF signaling we observed suggests a mechanistic molecular basis for the link between salpingitis and the risk of ectopic pregnancy, which has previously been connected to overexpression of LIF in the FT33." (PMID 30886143, 2019).
Stillbirth (1 paper, 2023). Death of the fetus in utero after at least 22 weeks of gestation. "Finally, an LIF gene polymorphism (rs3463076786: C/T) is associated with the number of stillbirths in pigs." (PMID 37510406, 2023).
synovial sarcoma (1 paper, 2022). "Compared with the control tissues (chronic synovitis), the mRNA expression of SOX-2, Nanog, OCT-4, LIF, LIFR and Ki-67 was significantly higher in the synovial sarcoma tissue samples (P = 0.0070, P = 0.0487, P = 0.0002, P = 0.0110, P < 0.0001, and P = 0.0011, respectively)." (PMID 35151264, 2022).
thymic atrophy (1 paper, 2011). "Work from this laboratory has previously shownthat injection of IL-6, as well as IL-6 family members LIF and OSM, actively induceacute thymic atrophy within three days." (PMID 21437240, 2011).
trophoblast tumor (1 paper, 2020). "Regarding to the results, it was foundthat the expression of the VEGF gene in trophoblast tumor cells treated by LIF was reduced in concentrationand time-dependent manners." (PMID 32681623, 2020). "In this study we aimed to evaluateVEGF gene expression levels in trophoblast tumor cellline (JEG-3) at different times, while these cells weretreated by different concentrations of LIF." (PMID 32681623, 2020).
Umbilical hernia (1 paper, 2018). Protrusion of abdominal contents through a defect in the abdominal wall musculature around the umbilicus. "Targeted sequencing of candidate genes within the region revealed polymorphisms within the Leukemia inhibitory factor (LIF) and Oncostatin M (OSM) that were significantly associated with umbilical hernia (P < 0.001)." (PMID 29843603, 2018).
tumor (325 papers, 2007 to 2026). "Previous studies have shown that SOX9 promotes immune evasion by secreting LIF to regulate tumor‐associated macrophage polarization and inhibit CD8+ T‐cell function, highlighting its central role in shaping an immunosuppressive microenvironment." (PMID 41270217, 2026). "Leukemia Inhibitory Factor (LIF) is a cytokine that contributes to this profound immunosuppression, which is thought to be at least partly mediated by pro-tumoral (M2-like) tumor-associated macrophages (TAMs)." (PMID 41809833, 2026). "LIF is a pleiotropic factor that has been shown to be associated with poor tumor prognosis in a wide range of tumors." (PMID 40703522, 2025). "Initially, we detected the protein expression levels of LIF in the PDX tissues obtained from two patients and found that upregulated LIF expression was associated with high tumor malignancy." (PMID 40416597, 2025). "Leukemia inhibitory factor (LIF), a pleiotropic cytokine, is robustly produced in tumor-associated macrophages, and its administration endows them with potent immunosuppressive traits." (PMID 40191202, 2025). "Conditioned medium from C26 tumor cells (which secrete high LIF) causes severe atrophy of cultured myotubes and robust STAT3 activation." (PMID 40869331, 2025). "LIF regulates CXCL9 in tumor-associated macrophages and prevents CD8+ T cell tumor-infiltration impairing anti-PD1 therapy." (PMID 38789520, 2024). "Circulating LIF levels were significantly associated with tumor size (p < 0.001), cervical node metastasis (p < 0.001), and clinical stage (p = 0.002) when the median values served as the cutoff." (PMID 39206755, 2024). "For example, C26 tumor-bearing mice exhibit progressive body weight loss and poor survival, which can be largely alleviated by LIF neutralizing antibody treatment." (PMID 38245529, 2024). "The effect of LIF expression level on tumor cachexia was detected by knockout of LIF, and it was found that weight loss, muscle loss, fat loss, and splenomegaly were improved in knockout mice." (PMID 37020597, 2023). "LIF can regulate CXCL9 in tumor-associated macrophages and prevent tumor infiltration of CD8+ T cells, explaining the slower CD8+ TILs kinetics seen with oBHV + ICI." (PMID 36831636, 2023). "Tumor cells and tumor associated fibroblasts can secrete leukemia inhibitory factor (LIF) and interleukin‐6 (IL‐6) to promote ECM remodeling and provide conditions for tumor cell migration." (PMID 36560848, 2023). "The LIF/LIFR axis is implicated in tumor growth and progression by acting on multiple aspects of cancer biology." (PMID 36358818, 2022). "We then mechanistically linked this stromal IL6/LIF expression with tumor ER signaling by demonstrating that IL6/LIF signaling both increases tumor cell ERα expression and induces ER reporter gene activation." (PMID 36230597, 2022). "Meanwhile, LIF mediates the crosstalk between cancer-associated stromal cells and tumor cells, which is significantly associated with advanced tumor stage, tumor volume, and a short overall survival time." (PMID 35740622, 2022). "Currently, it is unclear the role of LIF in metabolic reprogramming in different cell types in the tumor microenvironment, including tumor-associated fibroblasts and immune cells." (PMID 35440095, 2022). "Implicated CAF-derived factors in tumour development include TGFβ, LIF, CXCL12, IL6, IGF1, and MAPK and STAT3 signalling pathways." (PMID 36358721, 2022). "LIF signaling promotes tumor cells crosstalk with fibroblasts and is implicated in pro-invasive activation of stromal fibroblasts." (PMID 36358818, 2022). "The LIF/LIFR axis is implicated in tumor growth and progression by altering the magnitude of several oncogenic processes." (PMID 34400617, 2021). "A similar association between circulating LIF and intra-tumor nerve density was also observed in human PDAC samples." (PMID 33630157, 2021).
tumor (continued). "LIF has been shown to inhibit CD8+ T-cell entry while increasing tumor-associated macrophage and regulatory T-cell entry into other tumors, decreasing the efficacy of immune checkpoint blockade." (PMID 32733369, 2020). "Another tumor-derived cytokine, leukemia inhibitory factor (LIF), has been associated with MEK activation and other muscle catabolic processes." (PMID 33291708, 2020). "In mouse tumor xenografts, higher cellular LIF was also associated with increased tumor stromal invasion." (PMID 30504771, 2018). "Overexpression of LIF in tumors is often associated with poor survival, which substantiates a critical role of LIF in promoting tumor progression and metastasis." (PMID 26716902, 2016). "Using genes associated with previously reported classifications of classical and basal-like tumor cells, we determined that chemo/anti-LIF/anti-PD-L1 significantly decreased genes associated with basal-like tumors (Figure A10), consistent with the observed downregulation of EMT." (PMID 39857986, 2025). "In addition to its role in tumor progression, LIF has been associated with immune‐related toxicity in patients with gastrointestinal (GI) cancers receiving immune checkpoint inhibitors." (PMID 41163398, 2025). "Preliminary data suggest that high LIFR expression is associated with worse outcomes in advanced GC, while LIF expression may correlate with improved responsiveness to chemoimmunotherapy and favorable remodeling of the tumor immune microenvironment." (PMID 41163398, 2025). "In addition, LIF impairs anti‐PD1 therapy by modulating CXCL9 expression in tumor‐associated macrophages (TAM), ultimately disrupting the infiltration of CD8+ T cells into the tumor microenvironment." (PMID 40416597, 2025). "Furthermore, LIF overexpression is associated with a poor prognosis in cancer patients, indicating an important role of LIF in tumor progression." (PMID 38245529, 2024). "LIF overexpression in solid tumors has been reported to be associated with poor clinical outcomes in patients, which is supported by the observations that constant (stable) LIF overexpression in cancer cells promotes tumor progression in animal models." (PMID 38167344, 2024). "Another study showed that LIF, secreted by PSCs, was associated with tumor progression in PDAC." (PMID 38540204, 2024). "Our analysis of human tumor data hints that LIF may also have local effects supporting cancer-associated fibroblasts, a cell type that has recently drawn attention as key member of the tumor immune environment." (PMID 37134077, 2023). "Recent studies have implicated LIF-LIFR signaling in playing a key role in tumor growth, progression, metastasis, stemness and therapy resistance; the LIF-LIFR axis may be considered as a promising clinical target for cancer therapy." (PMID 37189418, 2023). "LIF signaling in cancer associated fibroblasts and carcinoma cells has been shown to cause extracellular matrix remodeling and actomyosin contractility to form a proinvasive environment for tumor cells." (PMID 35204717, 2022). "It was previously shown that in mouse models of both genetic and pharmacological LIF blockade, loss of LIF resulted in significantly impaired tumor progression and augmented chemotherapy efficiency, prolonging survival by modulating cancer cell differentiation and EMT." (PMID 34298706, 2021). "LIF upregulation causes tumor resistance to chemotherapy in colorectal cancer." (PMID 32651426, 2020).